TCF7 (transcription factor 7)
Diseases named in the same sentence as TCF7 in open-access papers (continued):
Sharing a sentence is not in itself a finding about the gene and the disease.
colorectal cancer (17 papers, 2011 to 2026). A primary or metastatic malignant neoplasm that affects the colon or rectum. "T-cell-specific transcription factor 7 (TCF7) is directly associated with colorectal cancer." (PMID 34753514, 2021). "For example, circ3823 was more stable than PVT1, promoting colorectal cancer growth, metastasis, and angiogenesis through the circ3823/miR-30c-5p/TCF7 axis, and it may serve as a new diagnostic marker or therapeutic target for the treatment of colorectal cancer patients." (PMID 35302432, 2022). "Previous studies have demonstrated that TCF7 can be used to independently predict worse OS in epithelial ovarian cancer, nonsmall lung cancer, and colorectal cancer." (PMID 36057947, 2023). "For example, circ3823 contributes to growth, metastasis and angiogenesis of colorectal cancer by absorbing miR-30c-5p and mediating TCF7." (PMID 35042525, 2022). "TCFs—particularly TCF7 and TCF7L2—have been implicated across different tumor types, with a particularly strong link to colorectal cancer." (PMID 27527215, 2016). "T-cell Factor/Lymphoid Enhancer Factor (TCF/LEF) transcription factors are major regulators of Wnt targets, and the products of the TCF7 and TCF7L2 genes have both been implicated in the progression of colorectal cancer in animal models and humans." (PMID 27527215, 2016). "TCF7 acted as an oncogene in colorectal cancer, gastric cancer and glioma." (PMID 41367628, 2025). "However, a number of studies demonstrated that TCF7 might act as a tumor suppressor and be diminished in leukemia, lymphomas, or colorectal cancers." (PMID 26289446, 2015). "Roles for LEF/TCF proteins has been studied in tissue-culture and animal models of intestinal stem cells and colorectal cancer, which suggested roles for TCF7L2 and TCF7 in normal colorectal tissue, where LEF1 and TCF7L1 are silent, but strong expression in colorectal tumor of LEF1 and TCF7." (PMID 32403323, 2020).
liver cancer (15 papers, 2017 to 2025). An epithelial or non-epithelial malignant neoplasm that arises from the liver. "Oncogenic lnRNA includes Transcription factor-7 (TCF7) which has been found at higher levels in liver cancer and was important for self-renewal." (PMID 40486878, 2025). "LncRNA T cell factor 7 (TCF7) binds to BAF170 and recruits the SWI/SNF complex to the TCF7 promoter to regulate its expression, leading to the activation of Wnt signaling and promoting the self-renewal of liver cancer stem cells (liver CSCs)." (PMID 35505438, 2022). "UCH37 can specifically bind and deubiquitinate transcription factor 7 (Tcf7) to activate Wnt signaling in human liver cancer cells." (PMID 33498168, 2021). "LncTCF7 recruits SWI/SNF complex binding to the TCF7 promoter and triggers TCF7 transcription and further activation of Wnt signaling-induced tumorigenic activity in liver cancer stem cells." (PMID 32466488, 2020). "Both TCF7 and TCF7 expression were observed in the sphere formation of liver cancer cells, indicating their importance in CSCs." (PMID 29299179, 2017). "Additionally, Lnc TCF7 recruits the transcription factor complex SWI/SNF to the TCF7 promoter region to regulate its expression, thus promoting the self-renewal and proliferation of liver cancer stem cells." (PMID 36380019, 2022). "Recently, it is found that lncTCF7 is highly expressed in liver cancer stem cells through recruiting the SWI/SNF complex to the promoter of TCF7 (transcription factor 7) to regulate its expression, leading to the activation of Wnt signaling in hepatocellular cancer stem cells." (PMID 33149126, 2020). "Biochemical analyses demonstrated that deubiquitinating activity of Uch37 is not involved in Tcf7 protein stability but is required for the association of Tcf7 to target gene promoter in both Xenopus embryo and human liver cancer cells." (PMID 28198400, 2017). "Moreover, we suggest that enzymatic activity of Uch37 is required for DNA binding of Tcf7 in Xenopus gastrula embryo and human liver cancer cells." (PMID 28198400, 2017). "In b_ILC1-XCL1, which is similar to the ILC2a cells found in liver cancer, genes such as XCL1, TCF7, and CD74 were highly expressed." (PMID 37762493, 2023). "The lncTCF7 is highly expressed in liver cancer and liver CSCs, recruits the SWI/SNF complex to the promoter of an adjacent gene TCF7 and promotes TCF7 expression in cis, finally driving Wnt signaling activation and liver CSC self-renewal." (PMID 38933287, 2023). "LncRNA TCF7 recruits SWI/SNF5 complexes to TCF7 promoter to mobilize nucleosomes and remodel chromatin conformation, promoting liver cancer stem cells self-renewal." (PMID 33868368, 2021). "LncRNA TCF7 induces TCF7 transcription through recruiting the SWI/SNF complex to its promoter, ultimately activating WNT signaling to inhibit liver cancer stem cell self-renewal." (PMID 32661324, 2020). "It is found that LncTCF7 is required for the self-renewal and tumor propagation of liver cancer stem cells, which functions based on the recruitment of SWI/SNF complex to the neighboring promoter of TCF7 to regulate its expression." (PMID 33149126, 2020). "LncRNA TCF7(transcription factor 7) recruits the SWItch/Sucrose Non-Fermentable (SWI/SNF) complex to the promoter of TCF7 that activates the Wnt signaling pathway to promote self-renewal of liver cancer stem cells." (PMID 37153158, 2023). "In addition, lncTCF7 was found to be significantly overexpressed in liver tumor tissues and liver cancer stem cells (CSCs); this lncRNA can recruit the SWI/SNF complex to the TCF7 gene promoter to regulate its expression, thus activating the Wnt signaling pathway." (PMID 34819106, 2021).
viral infection (10 papers, 2017 to 2025). "The transcription factor TCF1, encoded by the gene TCF7, is required for formation of a pool of renewable central memory T cells during viral infections." (PMID 38223410, 2024). "To determine whether the methylation status at Tcf7 locus is associated with antigen specific TFH differentiation during acute viral infection, we transferred naive SMARTA cells into naive recipient mice, then the chimeras were subsequently infected with LCMV Armstrong strain." (PMID 36045674, 2022). "In summary, this study reveals for the first time that EZH2 regulates the epigenetic modification of Tcf7 during acute viral infection." (PMID 36045674, 2022). "Further unbiased investigation into the most expressed genes per cluster revealed a plethora of genes previously reported in the context of viral infections, such as Il7r, Tcf7, Zeb2, Klrg1, Gzma, Gzmb, Gzmk, Vim, Lgals3, Tox, Lag3, Pdc1, Id3." (PMID 35185882, 2022). "Therefore, our findings suggested that EZH2 plays an important role in maintenance of hypomethylation at Tcf7 locus thus affecting TFH differentiation during acute viral infection." (PMID 36045674, 2022). "While Bcl6 also displayed a distinct motif enrichment pattern, its role appears more prominent in the D8MPEChi population compared to Tcf7 and Lef1, this is consistent with recent finding that Bcl6 is required for the generation of CD8+ memory precursors upon acute viral infection." (PMID 39804040, 2025). "Besides, compared all other T-cell subtypes, the CD38+HLA-DR+ T cells exhibited higher expression levels of interferon regulatory factors (IRF1 and IRF7) and T cell factor -7 (TCF7), indicating the host’s immune response against viral infection." (PMID 40370439, 2025).
glioma (9 papers, 2017 to 2025). A benign or malignant brain and spinal cord tumor that arises from glial cells (astrocytes, oligodendrocytes, ependymal cells). "Methylations of HES4 (FDR = 0.017) and NOV (FDR = 3.26E-3) were each significantly associated with later-onset gliomas, while TCF7 methylation was suggestively associated (FDR = 0.132)." (PMID 34788626, 2021). "TCF7, THY1, and TGFβ2 are all associated with glioma stemness, leading to immunosuppression." (PMID 35599254, 2022). "Furthermore, the loss of function assay revealed that knockdown of lncTCF7 significantly inhibited glioma cell migration, proliferation and tumorigenicity through upregulating E-cadherin or suppressing TCF7/Sox2 and CyclinD1 expression." (PMID 29234033, 2017). "In the validation cohort of glioma patients, we found that CCN4, LGR6, MMP7 and TCF7 were obviously upregulated." (PMID 34852024, 2021). "HES4-methylated IDHwt (FDR = 9.58E-3) and NOV-methylated IDHwt (FDR = 0.010) gliomas were both significantly enriched in the later-onset cohort, along with HES4-methylated IDHmut-codel (FDR = 0.015) and TCF7-methylated IDHmut-codel (FDR = 0.016) gliomas." (PMID 34788626, 2021). "In addition, DKK3 interacts with immune system-related proteins, including TCF7, THY1, and TGFβ2, and induces proliferation, angiogenesis, invasiveness, and immunosuppression of glioma cells." (PMID 35599254, 2022). "In a recent pan-cancer analysis of oncogenic pathways, WNT signaling was shown to be altered in around two-thirds of IDH-mutant, 1p/19q-codeleted low-grade gliomas, i.e. ODs according to the WHO classification of 2016, in that they exhibited inactivation of the TCF7 gene." (PMID 33929593, 2021). "Our data indicated that the Wnt pathway activation related genes such as CCN4, FOSL1, LGR6, MMP7, RAC2, SERPINF1 and TCF7 were upregulated, while Wnt pathway inactivation related gene such as CXXC4 was downregulated in radiotherapy treated glioma patients from TCGA database." (PMID 34852024, 2021).
pancreatic cancer (9 papers, 2020 to 2025). "We conditionally inactivated Tcf7 in CD4 expressing T cells in a mouse model of pancreatic cancer and observed changes in the tumor immune microenvironment, including more CD8+ T cells and fewer regulatory T cells, but also compensatory upregulation of PD-L1." (PMID 36239683, 2023). "To functionally dissect the role of T cell Tcf7 in pancreatic cancer, we generated Cd4-CreERT2;Tcf7fl/fl mice, where Tcf7 can be conditionally inactivated in CD4-expressing T cells." (PMID 36239683, 2023). "Heatmap analysis in colorectal, stomach, and pancreas cancer patient datasets showed a consistent overlap between LBH overexpression and WNT signaling genes associated with pathway activation, i.e., WNT2, WNT5A, WNT11, LEF1, TCF4 or TCF7, CCTNB1, CCND1, JUN, DKK3." (PMID 37268816, 2023). "We inactivated Tcf7 in CD4+ T cells and implanted pancreatic cancer cells from the well-characterized KPC mouse model into the pancreata of syngeneic C57BL/6J mice." (PMID 36239683, 2023). "Although there are scientific reports on the prognostic values of SMAD3 and CTNNB1 in pancreatic cancer, the precise functions of Jun Oncogene (JUN) and TCF-7 in the pathogenesis of pancreatic cancer are still largely unknown and require further understanding and research." (PMID 33194391, 2020).
COVID-19 (7 papers, 2020 to 2025). A disease caused by infection with severe acute respiratory syndrome coronavirus 2. "Additionally, we found 44, 42, and 53 up-DEGs that were notably associated with mild, moderate, and severe COVID-19, and there were six significant common genes across three phases of COVID-19, including TCF7, GZMH, RAB5IF, CCND2, BIRC6, and NDUFAF3." (PMID 35172892, 2022). "For example, PRDM1 (encoding BLIMP-1) in monocytes 40 and TCF family TFs (including TCF7) motifs in CD4 naive T cells are uniquely enriched in COVID-19 samples 40,41." (PMID 37425926, 2025). "Performing this analysis for the COVID-19 patients demonstrated clear B- and T-cell clusters, defined by expression of TCF7, LEF1 (clusters 0 and 1), CD74, CD79A (clusters 2 and 3), IL7R (cluster 4) and CCL5, NKG7, GNLY (cluster 6)." (PMID 33884369, 2021). "Among others, cytokine-related genes IL12B and TNFSF10 and members of the Krüppel-like factors (KLF) and CCAAT/enhancer-binding protein (CEBP) family of transcription factors as well as transcription factor 7 (TCF7) were affected only in COVID-19-derived PBMCs." (PMID 37614228, 2023). "Moreover, we performed further study with finding a similar high-low-high expression pattern of human SNHG1/VPS13D/IL7R/TCF7 in CD8 T cell subsets from PBMC samples of the convalescent COVID-19 patients." (PMID 33758164, 2021).
diabetes (7 papers, 2008 to 2025). "In their study, the genes GCKR, KCNJ11, and TCF7 were associated with hypertriglyceridemia and diabetes, while the LPIN1 and SLC22A1 genes were linked to a favorable response to antidiabetic drugs like rosiglitazone and metformin." (PMID 39408795, 2024). "TCF7 was revealed and regarded as diagnostic biomarker in type 1 diabetes mellitus." (PMID 36837510, 2023). "The same results were observed in a rat model of diabetes, in which miR-22 levels inversely correlate with TCF7 expression and promote the transcriptional inhibition of enzymes involved in gluconeogenesis." (PMID 39859495, 2025). "The role of miR-22 in diabetes is further supported by the role of miR-22 in impairing gluconeogenesis, through the downregulation of TCF7." (PMID 39859495, 2025). "Other migration-associated mutations were found in genes determining obesity and diabetes in human, mice, sheep, and cattle (e.g. gene UBE3D and TCF7)." (PMID 35143486, 2022). "These include CCND2, CILP2, PBX4, SH2B3, SLC6A4, TCF7 and KLF14, which have polymorphisms associated with diabetes risk." (PMID 27029739, 2016). "Ambiguous matches were found in TCF7 and TCF7L2, the later, a gene recently linked to the development of diabetes (but not DN)." (PMID 18698414, 2008).
lung carcinoma (7 papers, 2015 to 2025). "The dual roles of TCF7 in lung cancers were discussed and it is associated with the cellular proliferation, invasion or metastasis." (PMID 26289446, 2015). "Earlier, we confirmed that LINC00665 can upregulate the expression of HHLA2 in lung cancer cells by recruiting the transcription factor TCF7." (PMID 38951802, 2024). "FL-TCF7 is associated with the proliferation, invasion, or metastasis of lung cancer cells and the poor prognosis of patients with lung cancers, while dn-TCF7 shows therapeutic effect for cancer metastasis." (PMID 26289446, 2015). "Based on these analyses, we hypothesize that LINC00665 may promote the transcription of HHLA2 in lung cancer cells by recruiting transcription factor TCF7, thereby inhibiting NK cell cytotoxicity and promoting immune escape and the development of lung cancer." (PMID 38951802, 2024). "Based on this, we hypothesized that LINC00665 could promote the transcription of HHLA2 in lung cancer cells by recruiting the transcription factor TCF7, thereby participating in the regulation of NK cell cytotoxicity." (PMID 38951802, 2024). "It is possible that the down-regulation of CD3-ε in patients with lung cancer may be related to TCF7 dysfunction through the regulation of TCF7 in CD3E expression." (PMID 26289446, 2015). "However, there is currently no research reporting whether LINC00665 can promote the expression of HHLA2 in lung cancer cells and inhibit NK cell cytotoxicity by targeting binding TCF7, leading to immune escape and the development of lung cancer." (PMID 38951802, 2024). "The results showed that, compared to adjacent tissues, the expression of TCF7 and HHLA2 mRNA in tumor tissues of lung cancer patients was significantly elevated (all P < 0.001)." (PMID 38951802, 2024). "Further analysis revealed that LINC00665 recruits transcription factor TCF7 to upregulate HHLA2 expression in lung cancer cells, thereby facilitating lung cancer development and immune escape." (PMID 38951802, 2024). "Western blot analysis showed that TCF7 and HHLA2 were significantly upregulated in different lung cancer cell lines (all P < 0.05)." (PMID 38951802, 2024). "LINC00665, through recruitment of TCF7 and upregulation of HHLA2, inhibits NK cell cytotoxicity, promoting the development and immune evasion of lung cancer." (PMID 38951802, 2024). "Western blot results demonstrated that knocking down LINC00665 or TCF7 (all P < 0.001) significantly decreased the expression of HHLA2 in lung cancer cells (all P < 0.05)." (PMID 38951802, 2024). "In conclusion, our study unravels a novel regulatory network involving LINC00665, TCF7, HHLA2, and immune escape in lung cancer." (PMID 38951802, 2024). "To validate this hypothesis, we first used qRT-PCR to detect the expression of TCF7 and HHLA2 in tumor tissues of lung cancer patients and metastatic lung cancer patients." (PMID 38951802, 2024). "LINC00665, TCF7 mRNA, and HHLA2 mRNA expression levels were significantly higher in lung cancer tissues than adjacent tissues, with non-metastatic lung cancer showing higher expression than metastatic lung cancer." (PMID 38951802, 2024).
colon carcinoma (6 papers, 2014 to 2025). "Then, we inquired through the GEPIA website that TCF7 was significantly highly expressed in both rectal cancer and colon cancer." (PMID 34172072, 2021). "In addition, GEO data showed that TCF7 was closely related to the histopathological grade of colon cancer." (PMID 34172072, 2021). "As downstream factors in wnt/β-catenin signaling, both TCF7 and LEF1 levels were up-regulated in some tumors such as colon cancers." (PMID 26289446, 2015). "AXIN2, LEF1, TCF7, and PROX1 were highly expressed in colon cancer compared with control samples." (PMID 37584250, 2023). "However, β-catenin and RAC1 were observed to interact with the TCF7 or LEF1 promoter region in both breast and colon cancer cells." (PMID 30650643, 2019). "We used this colon carcinoma cell line rather than HeLa cells because the Wnt signaling pathway is activated and significant levels of TCF7 and MSI1 protein are expressed relative to HeLa cells." (PMID 24551047, 2014). "FOXO1 inhibition impacted AXIN2, LEF1, and TCF7 in some, but not all, examined BBC and colon cancer cell lines." (PMID 37584250, 2023).